TET2 (tet methylcytosine dioxygenase 2)
Diseases named in the same sentence as TET2 in open-access papers (continued):
Sharing a sentence is not in itself a finding about the gene and the disease.
cancer (continued). "The expression of TET2 was decreased in most female cancers, and its high expression was distinctly associated with the favorable prognosis of most female cancers." (PMID 35223782, 2022). "Clonal hematopoiesis driven by TET2 and other mutations is evidently associated with multiple disease risks, from cancer to CVD to chronic obstructive pulmonary disease, as reviewed above." (PMID 35726685, 2022). "Studies over the last decade have revealed the striking presence of cancer‐associated mutations in what appear to be healthy tissues, as first shown for TET2 mutations in the blood of elderly people." (PMID 35726685, 2022). "According to the analysis, TET2 mutation was correlated with a poor prognosis in TET2-mutated female cancers." (PMID 35223782, 2022). "In terms of the molecular mechanism, 5-hmC is a product of DNA demethylation of TET2, suggesting that loss of TET2 leads to loss of 5-hmC, which can promote cancer occurrence and progression by affecting gene expression patterns." (PMID 35480097, 2022). "The results revealed that mutation in the TET2 gene was the most common genetic alteration found in most patients with selected cancers." (PMID 35223782, 2022). "For example, CHIP clones marked by TET2 mutations lead to the production of mature myeloid cells that produce inflammatory cytokines, and inflammation is associated with cancer evolution." (PMID 35726685, 2022). "The association between TET2 expression and prognosis of patients with various cancer types was analyzed using data obtained from TCGA and GEO." (PMID 35223782, 2022). "TET2 mutated HSC clones are frequently found among healthy aged individuals characterized by an increased risk of cancer onset and a higher propensity to develop cardiovascular diseases." (PMID 35159097, 2022). "TET loss-of-function is strongly associated with cancer, with TET2 loss-of-function mutations frequently observed in hematological malignancies that are resistant to conventional therapies." (PMID 34930302, 2021). "Significant inhibition was achieved in cancer cells and animals bearing tumors that harbor deleterious TET2 and nonsynonymous DNMT3A mutations." (PMID 34039392, 2021). "Loss of TET2 is associated with increased resistance of cancer cells to chemotherapy in vitro and in vivo." (PMID 34885145, 2021). "Previous reports have showed that the downregulation of TET2 expression and 5hmC levels is an epigenetic hallmark of multiple types of cancers." (PMID 34064441, 2021). "Although three genes, DNMT3A, ASXL1 and TET2, are hot genes, CH mutations also appear in other genes, particularly some driver genes that are indicators for cancer therapy." (PMID 34658138, 2021). "By contrast, the role of previous cancer treatment in TRMN emergence in TRMN with TET2/DNMT3A mutations is uncertain." (PMID 34423258, 2021). "In conclusion, the present findings are in line with previous studies of TET2 mutations in model organisms and human cancer, as well as human germline TET2 haploinsufficiency." (PMID 34663818, 2021). "UCEC exhibited a significantly higher number of mutations across pan-cancers, analogously TET2, DNMT3B, DNMT3A, and DNMT1 have placed a moderate burden in m5C regulator genes." (PMID 34325709, 2021). "TET2 mutations are more frequent in “mature” type hematopoietic cancers, consistent with its defined function in terminal differentiation/maturation within both myeloid and lymphoid lineages." (PMID 36618446, 2021).
cancer (continued). "Tet2 deficiency leads to impaired homologous recombination DNA repair and decreased expression of breast cancer susceptibility genes (BRCAs), and the reduction in BRCA gene expression sensitizes tumor cells to PARPis." (PMID 34222235, 2021). "IDH enzymes normally produce α-ketoglutarate (αKG), however, cancer cells with mutated IDH1/2 produce 2-hydroxyglutarate (2-HG) which is detrimental to TET2, because TET2 uses αKG as a co-activator, resulting in TET2 having impaired functionality." (PMID 32781570, 2020). "TET loss-of-function is strongly associated with cancer; TET2 loss-of-function mutations are frequently observed in hematological malignancies that are resistant to conventional therapies." (PMID 33520997, 2020). "TET2 loss is associated with human cancers but its role in the mammary gland development and tumorigenesis is unclear." (PMID 32934200, 2020). "Loss of TET2 expression in particular is correlated with metastasis, increased Gleason score, and worse cancer-specific survival in PCa patients." (PMID 33008340, 2020). "Recent studies have shown that aberrant expression of TETs and 5hmC levels are associated with tumorigenesis in different types of cancers, and TET2 is frequently mutated in hematological malignancies." (PMID 30045709, 2018). "In fact, the overexpression of TET2 has been reported to induce higher 5-hmC levels in genes that are associated with cancer-related pathways, such as genes that code for focal adhesion and adherens junction proteins." (PMID 27852070, 2017). "Although TET2 mutations frequently occur in various types of haematological malignancies, the mechanism by which they increase risk for these cancers remains poorly understood." (PMID 28440315, 2017). "Analysis of this data shows that some epigenetic proteins such as DNMT3A, HDAC2, KDM6A, TET2 are highly mutated in most of the cancer cell lines." (PMID 26777304, 2016). "Several mechanisms have been reported for the dysregulation of TET2 in cancers, including mutation of TET2 gene and decreasing TET2 mRNA expression level." (PMID 26816554, 2016). "In our analysis, we found that epigenetic proteins DNMT3A, HDAC2, KDM6A, and TET2 are highly mutated in variety of cancers." (PMID 26777304, 2016). "While TET2 mutations are thought to be driver mutations in haematopoietic malignancies, whole-exome sequencing of large cancer cohorts has revealed only rare mutations in TET1 or TET3 (refs 19, 48, 49)." (PMID 26607761, 2015). "Here, we discuss the role of TET proteins in cancer focusing on TET2 mutations and activity impairment, first in hematopoietic malignances and then in solid tumors." (PMID 25632305, 2015). "Up-regulation of TET2 expression in cancer has been associated with MET; and therefore, a more differentiated state." (PMID 25229454, 2014). "Although the temporal relationship between TET2 mutations and other leukemogenic drivers is still unclear, the frequency and ubiquitous nature of these mutations in cancer is quite revealing." (PMID 24622842, 2014). "Interrogation of the mutation status of TET2 in the Human Cancer Genome database revealed that Jurkat was the only cell in our panel that had pathological changes (p.Q831H)." (PMID 24405639, 2014). "Of the many mutations that characterize myeloid malignancies, some (TET2, ASXL1) can initiate a preleukemic clone, whereas others (MPL, JAK2) are phenotypic lesions that trigger the overt malignant disease." (PMID 23397042, 2013). "Cancer-associated mutations in isocitrate dehydrogenase are proposed to impair TET2-dependent DNA demethylation." (PMID 23863747, 2013).
cancer (continued). "Data surrounding the TETs are particularly limited in rarer cancer types; however, somatic TET2 mutations have been described in a number of these settings, including salivary duct carcinoma, penile squamous cell carcinoma, parathyroid carcinoma, and oligoastrocytoma." (PMID 40116537, 2025). "Furthermore, data concerning the effects of TET2‐mutant allele dosage in cancer development is scarce, and relatively few studies have sought to differentiate between monoallelic and biallelic TET2 mutations in humans." (PMID 40116537, 2025). "However, there is a paucity of collated data on the frequency of TET2 mutations in solid human cancers." (PMID 40116537, 2025). "The increased DNA 5mC methylation caused by TET2 targeting to RNA agrees with the widespread DNA hypomethylation or chromatin opening after TET2 inactivation frequently observed in embryonic stem cells, haematopoietic stem cells and cancer cells." (PMID 39358506, 2024). "Finally, we performed sequencing for epigenetic regulators, for example, DNMT3a and TET2 that are frequently mutated in cancers, in sorafenibR Hep3b and Huh7 cells." (PMID 38528605, 2024). "Additionally, our study, in alignment with prior studies, demonstrates DNMT3A and TET2 to be the common genes to be mutated among cancer cohorts." (PMID 39456832, 2024). "TET2 mutations drive tumorigenesis in several cancers, particularly in myeloid malignancies." (PMID 38929174, 2024). "TET2 is implicated in human malignancies such as lung, breast, skin, and kidney cancers and frequently in angioimmunoblastic and peripheral T-cell lymphomas and several types of leukemia, and a broad spectrum of cancer cell lines." (PMID 39057134, 2024). "We could demonstrate that mutations observed in MDS cancer cells, including in TET2 and IDH1/2 genes, are also generally observed in NK cells." (PMID 36737440, 2023). "TET2 mutations with importance in epigenetic regulation were identified in several human cancers." (PMID 38139831, 2023). "TET2 mutational inactivation decreases 5-hmC levels in several malignant tumors." (PMID 36732324, 2023). "Consequently, the association between TET2 genetic alterations and the prognosis of patients with selected cancers was assessed." (PMID 35223782, 2022). "Germline TET2 mutation might have a family aggregation, and TET2 may be a predisposition gene for haematological malignancy under the other gene mutations as the second hit." (PMID 35279121, 2022). "In this study, a conjoint analysis of TET2 was performed using data from TCGA and GEO to assess the following aspects: transcriptional level, clinical outcomes, DNA methylation, genetic mutations, cancer immune infiltration, and related signaling pathways." (PMID 35223782, 2022). "TET2 deletion promotes self-renewal in HSCs and impairs differentiation of HSPCs at multiple stages, leading to a state of predisposition toward various hematopoietic malignancies." (PMID 36203205, 2022). "Therefore, this study suggested that TET2 expression was significantly correlated with clinical prognosis, DNA methylation, gene mutation, and cancer immunology in female cancers." (PMID 35223782, 2022). "The changes in DNA methylation that result from somatic TET2 mutations have been studied in cancer and in mouse models, but whether and to what extent these mutations cause DNA methylation changes in CHIP and CCUS has not been addressed." (PMID 34663818, 2021). "Notably, the deleterious TET2 L1721W missense mutation was recurrent and found in 35.3% (6/17) of cancer lines examined." (PMID 34039392, 2021). "Importantly, TET2 loss causes the deregulation of expression of several genes involved in stem cell renewal or differentiation and cancer, and can also promote the accumulation of other mutations." (PMID 32748835, 2020). "Therefore, somatic TET2 mutations contribute to myeloid expansion and innate immune dysregulation with age and contribute to prevalent diseases in the developed world—cancer and cardiovascular disease." (PMID 31963585, 2020).
cancer (continued). "Lost expression of a key DNA demethylation enzyme TET2 is associated with human cancers and has been linked to stem cell traits in vitro; however, whether and how TET2 regulates mammary stem cell fate and mammary tumorigenesis in vivo remains to be determined." (PMID 32934200, 2020). "Certain Tet2-KO cancers have AID-mediated somatic mutations." (PMID 33184433, 2020). "Although this is not always the case, TET2 mutation frequently occurs before the JAK2V617F mutation in the development of MPN, suggesting that TET2 mutation may occur very early in cancer development." (PMID 25632305, 2015). "This could be a consequence of genetic alterations in enzymes regulating epigenetic patterns, such as gene mutations found in human myeloid malignancies, including DNMT3a, TET2, IDH1, IDH2, EZH2, or ASXL1." (PMID 24944583, 2014). "As an epigenetic biomarker of ENKTL, TET2 mutation is significantly associated with the loss of protein expression and is correlated with shorter overall survival, suggesting that TET2 may be involved in the cancer-driving process of ENKTL." (PMID 40433378, 2025). "Notably, TET2 mutations can cause cancer such as acute myeloid leukemia." (PMID 38042791, 2023). "Thus, there is ample evidence to suggest that TET2 loss may act as a key mechanism of PCa development, and exploration of its downstream target genes may provide new insights into cancer biology." (PMID 30917865, 2019). "Thus, we hypothesized that the CR domain might play a role in the association between TET2 and chromatin, and predicted that mutations in the CR domain associated with cancer might affect chromatin interactions." (PMID 28130413, 2017). "Similar to the NSCLC validation cohort, patients with TET2-mutant CHIP from the pan-cancer cohort had the highest frequency of TI-CH (33%, 381/1191), followed by ASXL1-mutant (32%, 124/392), DNMT3A-mutant (25%, 926/3,753), and PPM1D-mutant CHIP (13%, 83/622)." (PMID 40267425, 2025). "In these cancers, TET2 knockdown reduces SCC populations and increases apoptosis, highlighting its role in SCC survival and therapy resistance." (PMID 40196510, 2025). "In vitro studies demonstrated that TET2 knockdown CD19 CAR T cells exhibited comparable cytolytic activity against CD19-positive cancer cells compared to conventional CD19 CAR T cells." (PMID 40012079, 2025). "In PDX primary to liver metastasis trajectory, we also found a dramatic switch between Tet2 and Dnmt1 at the earlier time points, two enzymes with opposing functions in DNA methylation, which is known to be aberrant in cancer." (PMID 39748426, 2025). "Since we found that the TET2 gene was top, it is important to point out that it is a key player in epigenetics, hematopoiesis, and cancer biology." (PMID 41440942, 2025). "The influence of TET2 on cell proliferation and apoptosis is a critical aspect of its biological function, particularly in the context of cancer." (PMID 41169875, 2025). "Alterations in the DNA methylation‒demethylation balance that support cancer stemness can also result from dysregulated tet-methylcytosine dioxygenase 2 (TET2) activity." (PMID 40744921, 2025). "The potential for novel drug development targeting TET2 is expanding, particularly in the context of its role in cancer and immune response modulation." (PMID 41169875, 2025). "In particular, the effect of DNMT1 status on the TET2 phenotype following DNMTi treatment remains elusive in cancer cells." (PMID 39057134, 2024). "The expression of TET1, TET2, and TET3 positively correlated in pan-cancer, with a stronger positive correlation observed between TET2 and TET3." (PMID 39104395, 2024). "Its deletion made the cancer cells prone to TET2 upregulation and activation of tumor suppressor expression upon DNMT inhibitor challenge." (PMID 39057134, 2024).
cancer (continued). "We found that deleting the DNMT1 gene made cancer cells prone to increased TET2 expression and re-expression of p16 after drug treatment." (PMID 39057134, 2024). "Although the oncogenic mechanisms of DNMT3A and TET2 should be further explored, they have a wide range of applications as potential therapeutic targets for cancer." (PMID 38246976, 2024). "Consistent with the need to maintain TET function in order to avoid cancer, two clinical trials are leveraging vitamin C, which activates TET2, in TET2 mutant hematologic malignancies (NCT03397173 and NCT03433781)." (PMID 38914477, 2024). "Given the dual function of TET2 in cancers, these findings demonstrate that a transcriptional complex of DNMT3a, TET2 and HDAC2 exists in sorafenibR HCC cells." (PMID 38528605, 2024). "Cancer stem cell-like cells (CSCs) displayed DNMT3a and TET2 overexpression, which were insensitive to sorafenib." (PMID 38528605, 2024). "We discovered that FAM110B expression often showed a favorable correlation with pan-cancer gene expression associated with m1A, m5C, and m6A, particularly in YTHDF3, YTHDC1, NSUN3, TET2, and METTL14." (PMID 39170745, 2024). "The results depicted in the Boxplot revealed that the expression level of the TET3 gene ranked highest across pan-cancer samples, followed by TET2, with TET1 exhibiting the lowest expression." (PMID 39104395, 2024). "TET2 shows promise as a powerful predictive biomarker for cancer prognosis and immunotherapy response in CRC." (PMID 38356721, 2024). "TET2 is considered an eraser of m5C52 and plays an important role in maintaining epigenome plasticity and in cancer development." (PMID 37488178, 2023). "Other cancer-related gene mutations identified by our WES analysis included SATB2, NOTCH3, STAG2 and TET2." (PMID 38201285, 2023). "As demonstrated in the current study, nuclear β-catenin induces nuclear translocation of TET2 and enables TET2 to induce DNA demethylation, which subsequently suppresses cancer progression." (PMID 37620362, 2023). "Other candidates that were among the DEGs in mutant TET2 flies and have been reported to be generally dysregulated in cancers include MMPs and other enzymes." (PMID 36989121, 2023). "Mutations in TET2, PTPRT, and LRP1B are associated with favorable responses to ICIs in other cancer types." (PMID 37654198, 2023). "Considering concerns about the potential lack of specificity when directly manipulating TET2 in CAR T cells and TET2’s role in cancer, we compared the tissue-specific expression levels of TET2, TOX, and TOX2." (PMID 37467321, 2023). "In SW480 cells, IWR1 treatment resulted in the translocation of Tet2CD from the nucleus to the cytosol, impaired TET2-induced DNA demethylation, facilitated the growth of cancer cells and decreased the expression of RORA and SPARC." (PMID 37620362, 2023). "Tet2 is necessary for both the development of cancer and anticancer immune responses, as well as the cross-talk between the immune system and cancer." (PMID 36672677, 2023). "The inhibition of the proliferation of healthy primary fibroblasts induced by the overexpression of TET1 and TET2 is in agreement with the results of studies on various cancer cell lines." (PMID 37371754, 2023). "The functional crosstalk between TET2 and mTORC1 revealed in this study not only has important implications in cancer biology, but also provides therapeutic strategy for the clinical treatment of various tumors with TET2 mutations or inactivation." (PMID 37550284, 2023). "As demonstrated in the heatmap, these genes were found to be positively correlated with TET2 expression in all female cancers except UCS." (PMID 35223782, 2022).